CD4 (CD4 molecule)
Diseases named in the same sentence as CD4 in open-access papers (continued):
Sharing a sentence is not in itself a finding about the gene and the disease.
glioblastoma (continued). "Quantitative analysis of chemokine receptor expression revealed a significant increase in the proportion of CCR2+CD4+ Tcm and Treg cells in glioblastoma compared to blood samples from the same patients." (PMID 35464424, 2022). "Tumor infiltrating lymphocyte (TILs) obtained from glioblastoma patient’s tumor specimens (n = 4) were evaluated for the presence of CD4+, CD8+, T reg (CD25+ FOXP3), and microglia (CD11b + CD45), through flow cytometry." (PMID 36299858, 2022). "Strikingly, all glioblastoma CD4+ T-cell subsets highly expressed CCR5, and CCR5 expression was significantly enriched in glioblastoma T cells compared to blood." (PMID 35464424, 2022). "T-cell subset analysis of tumor cell suspensions revealed that glioblastomas are mainly infiltrated by CD4+ and CD8+ CD45RA- memory T-cells." (PMID 35474089, 2022). "To explore the diversity of the T cells that are present in the glioblastoma microenvironment, we isolated CD4+ and CD8+ T cells by two different but complementary in silico methods." (PMID 35177622, 2022). "CXCR3+ cells were abundant in all CD4+ T-cell subsets, however enrichment was only statistically significant in CD4+ Tem and Tregs in glioblastoma biopsies compared to paired blood samples." (PMID 35464424, 2022). "Categorical scoring for the T cell markers CD3, CD8, CD4 and PD-1 indicated that the density of TILs across both primary and recurrent glioblastoma tumours was low." (PMID 34676050, 2021). "Recent studies have shown that the higher CD4 + T cell density and CD4/CD8 ratio were associated with worse OS in tumor, including ductal carcinoma in situ, glioblastoma, and GC." (PMID 33843442, 2021). "The aim of our study was to investigate the synergetic mechanisms of CD204+TAMs and CD4+TILs in glioblastoma microenvironment and to determine how these immune cells affect tumour recurrence." (PMID 35201470, 2021). "Glioblastomas with a high expression of CD204+TAMs and a low expression of CD4+TILs were associated with late recurrence." (PMID 35201470, 2021). "Cases with a high expression of CD204+TAMs and a low expression of CD4+TILs had late tumour recurrence and was more frequently present in IDH1wildtype type glioblastomas (77%)." (PMID 35201470, 2021). "In a different study, in patients with glioblastoma, CD4+ T-cell responses were dominant in the case if mutant (nested) MHC class I-restricted epitopes were used for vaccination." (PMID 34335558, 2021). "Evidence for the therapeutic utility of helper T cells is shown in murine models of glioblastoma multiforme where CD4+ CAR-T cells were found to perform better than CD8+ CAR-T cells, particularly in terms of exhibiting long-term anti-tumor immunity." (PMID 33679807, 2021). "In our study, we revealed that CD204+TAMs were highly expressed in the microenvironment of 71% of our glioblastoma samples whereas there were fewer CD4+TILs in the glioblastoma microenvironment." (PMID 35201470, 2021). "In this study, we assess the expression of M2-polarized TAMs (CD204) in the glioblastoma microenvironment and their relationship with circulating TILs, mainly CD4+TILs, as well as resident microglia." (PMID 35201470, 2021). "In p50−/− mice injected intracranially with syngeneic glioblastoma cells, CD4+ T‐cell depletion completely eliminated slowed tumor growth, whereas CD8+ T‐cell depletion only partially obviated the effect." (PMID 33480449, 2021). "Because IDH1 mutation is considered a major prognosticator in glioblastoma, we report a correlation between CD204+TAMs and CD4+TILs with IDH1 mutation." (PMID 35201470, 2021). "Relatedly, a previous study found that clinical outcomes of glioblastoma are positively correlated with the number of CD4+ and CD8+ T cells." (PMID 33726710, 2021). "The expressions of CD204+TAMs, CD4+TILs, and Iba1+microglia were quantitively assessed in 45 glioblastomas using immunohistochemistry." (PMID 35201470, 2021).
glioblastoma (continued). "CD4+ T cell responses are crucial for inducing and maintaining effective anticancer immunity; however, in glioblastoma and many solid tumors, HLA-II complexes are hardly ever naturally expressed." (PMID 33592498, 2021). "Consistently, examination of the transcriptomic data from the Ivy Glioblastoma Atlas Project demonstrated the enrichment of MDMs in the microvascular compartment, in which CD4+ and CD8+ T cells were found in IDH WT gliomas." (PMID 34571910, 2021). "CD4+TILs were highly expressed in 10 cases (22%) of glioblastomas, and 35 cases (77.8%) showed low expression." (PMID 35201470, 2021). "Cancer cells and TAMs induce CD4+FoxP3- type I regulatory T cells (Tr1) cells in glioblastoma (GBM) patients." (PMID 32595638, 2020). "Glycoprotein A repetitions predominant (GARP) is also expressed on the surface of glioblastoma cells, where it downregulates interferon-γ production by activating CD4+ T cells." (PMID 33396284, 2020). "A recent study on glioblastoma-targeted CAR-T cells claimed that CD4+ CAR-T cells performed a long-term antitumor response superior to CD8+ CAR-T cells." (PMID 31379876, 2019). "The amount of tumor infiltrating CD4+ leukocytes in glioblastoma correlates with tumor progression and presumably relates to tumor angiogenesis." (PMID 31023364, 2019). "The CD4+ helper T cell activation marker CD 40 ligand (CD40L) was also expressed in parvovirus-treated glioblastomas." (PMID 29244745, 2017). "Tregs also represent an increased fraction of the remaining CD4 compartment in patients with glioblastoma." (PMID 24273748, 2013). "One of the hallmark features of glioblastoma multiforme (GBM), the most common adult primary brain tumor with a very dismal prognosis, is the accumulation of CD4+CD25+Foxp3+ regulatory T cells (Tregs)." (PMID 23720663, 2013). "U373-MAGI-CXCR4CEM cells are human glioblastoma cells that have been transduced to constitutively express CD4 and CXCR4." (PMID 24156270, 2013). "In vitro analysis of peripheral CD4+ cells in glioblastoma patient also revealed a prominent Tr1 response against tumor cells suggestive of an enriched population of Tr1 cells in this setting." (PMID 23874336, 2013). "The work in progress has also shown, in different treated tumours described here, an increased percentage of T CD25 (interleukin-2 receptor), in the context of CD4, which has confirmed the results obtained in glioblastoma treatment." (PMID 22400112, 2012). "ITGB2 participates in immune activities related to glioblastoma, influencing B cells, CD4+ T cells, macrophages, neutrophils, and dendritic cells, and plays roles in energy metabolism, cell cycle regulation, angiogenesis, and neuronal myelin formation and repair after ischemic stroke." (PMID 41459526, 2025). "Their CDR3 sequence LPVSF is commonly found in public databases yet annotated for TRAV CDR3 in CD4+ T cells αβTCRs and has been identified in-house in Glioblastoma TIL and γδ cells from healthy donor peripheral blood, albeit each time as VαCδ hybrid clonotypes though (unpublished data)." (PMID 41306962, 2025). "Moreover, glioblastoma PDX model was created by seeding patient-derived glioblastoma cells in the brain of immunodeficient mice which received transfusion of CD4+ and CD8+ T cells containing synNotch-CAR T cells after 10 days." (PMID 38520648, 2024). "Furthermore, glioblastoma patients have less CD4+ T memory cells (5.537% more in epilepsy, 95% CI: 0.577 – 10.490, p = 0.029) than patients with epilepsy, but this was not the case when compared to healthy controls." (PMID 38318180, 2024). "In comparison to healthy donors, glioblastoma patients showed low frequencies of naive CD4+ T cells, CD4+ regulatory T cells, alternative monocytes, and intermediate monocytes, and high frequencies of memory B cells, mature NK cells, activated NK cells, DN T cells, and dendritic cells." (PMID 38318180, 2024).
glioblastoma (continued). "Importantly, our data also show that stimulation caused differential BAT3 changes in CD4+ T, CD8+ T, and NK cells from healthy donors compared to glioblastoma patients." (PMID 39513882, 2024). "One of the main immunotherapeutic platforms consists of viral oncolytic therapy, which has the dual effect of i) direct killing of tumor (glioblastoma) cells and ii) the dying cells release neoantigens that can attract APCs and, in turn, activate CD4+ and CD8+ T cells." (PMID 39399167, 2024). "Furthermore, previous studies have shown that pilocytic astrocytomas exhibit a significantly lower percentage of CD8+ T cells and NK T cells than glioblastomas, and PD-1+/CD4+ T cells are more enriched in medulloblastomas than in pilocytic astrocytomas." (PMID 38540119, 2024). "Thus, without correcting for any possible confounder, patients with epilepsy had 10.817% more naive CD4+ T cells than our reference group glioblastoma (95% CI: 5.754 – 15.880, p =4.11•10-5)." (PMID 38318180, 2024). "The analysis of the percentage cells per subsets between groups revealed that glioblastoma patients have fewer more CD4+ T cells than patients with epilepsy (8.483% more in epilepsy, 95% CI: 1.918 – 15.04, p = 0.012), after correction for sex, age, and dexamethasone." (PMID 38318180, 2024). "Compared to patients with medically refractory epilepsy, patients with a glioblastoma showed low frequencies of naive CD4+ T cells, CD4+ memory T cells, naive CD8+ T cells, and alternative monocytes, and high frequencies of dendritic cells, memory B cells, and B cells." (PMID 38318180, 2024). "Furthermore, RRMS patients had higher fractions of activated CD4+ TSCM compared to glioblastoma patients." (PMID 39497174, 2024). "Furthermore, direct comparison between RRMS and glioblastoma patients identified an increase in activated CD4+ TSCM in RRMS patients." (PMID 39497174, 2024). "It is therefore tempting to speculate that an oHSV-1 virus containing CIITA may synergically increase the stimulation of the tumor specific CD4 + T cells to reach complete rejection of in vivo established glioblastoma tumors." (PMID 39334370, 2024). "We observed a drop in naive CD4+ T cells in glioblastoma compared to both control groups." (PMID 38318180, 2024). "Similarly, the percentages of FOXO1 and BLIMP1 were also reduced in glioblastoma versus healthy donor CD4+ and CD8+ T cells and NK cells." (PMID 39513882, 2024). "This was significant as CD4 lymphopenia is frequently found in patients with glioblastoma and might be a basis for resistance to PD‐1 inhibitors." (PMID 39169517, 2024). "For example, CD4+ CAR-T cells were better than CD8+ CAR-T cells at controlling glioblastoma growth." (PMID 38143765, 2023). "Our investigation has revealed a positive correlation between elevated FDX1 expression in glioblastoma multiforme (GBM) patients, increased levels of tumor-associated macrophages, and reduced expression of CD4 + and CD8 + T cells, aligning with previous findings." (PMID 38114959, 2023). "Representative histograms for CD4+ T-cell subsets illustrate the typical chemokine receptor expression patterns observed, and demonstrate that staining for CCR2, CCR5, CXCR3 and CXCR6 was robust in glioblastoma-infiltrating T-cell populations compared to matched blood naïve CD4+ T cells." (PMID 35464424, 2022). "Similarly, targeting GITR in a glioblastoma model using an agonistic antibody promoted CD4 Treg differentiation into CD4 Teffs, alleviated Treg-mediated suppression of anti-tumor immune response, and induced potent anti-tumor effector cells." (PMID 36591244, 2022). "In line with previous results, CD4+ Tem was the predominant CD4+ T cell subset inside glioblastoma." (PMID 36497232, 2022). "Interestingly, a marked increase in GITR expression was observed in circulating CD4+ T cells in glioblastoma patients in the present study." (PMID 36497232, 2022).
glioblastoma (continued). "Then, dexamethasone can lower the number of CD4 lymphocytes in patients with glioblastoma treated with radiation alone or in combination with temozolomide, and this attenuated CD4þ lymphocyte count is associated with increased infections and decreased survival." (PMID 36056409, 2022). "Together, our flow cytometry analysis demonstrates that CCR5 and CXCR6 are expressed by large proportions of all glioblastoma-infiltrating CD4+ T-cell subsets, whereas CCR2 and CXCR3 enrichment was only observed in glioblastoma-infiltrating CD4+ Tcm and Tregs, and Tem and Tregs respectively." (PMID 35464424, 2022). "Similarly, CD4+ T TILs were shown to differentiate into Tregs when co-cultured with TAMs from glioblastoma patients." (PMID 34089486, 2021). "Glioblastoma with a dense CD204+TAMs and few CD4+TILs is associated with IDH1wildtype." (PMID 35201470, 2021). "TILs expressing CD4+ or CD8+ represent 0.25% of all cells in the glioblastoma microenvironment." (PMID 35201470, 2021). "Studies on glioblastoma-derived exosomes also show that ExoPD-L1 binds to CD4+ and CD8+ T cells." (PMID 33178688, 2020). "In glioblastoma patients, a high CD4 to CD8 ratio was a predictor of worse survival outcomes." (PMID 32355162, 2020). "In addition, another phase I trial showed that personalized neoepitope vaccine (APVAC2) induced predominantly CD4+ Th1 cell responses among 15 glioblastoma patients." (PMID 31492199, 2019). "Tumors lacking central memory CD4 T cells or natural killer cells were associated with better prognosis in glioblastoma, as verified by immunohistochemical analysis." (PMID 31451090, 2019). "In this study, CXCR7-mediated viral entry of HIV-1 and HIV-2 strains was demonstrated experimentally using a novel in vitro cellular infection model, in which CXCR7 was the sole chemokine receptor overexpressed on the surface of human U87 glioblastoma cells along with CD4, the main HIV receptor." (PMID 29560468, 2018). "Second, dexamethasone can lower the number of CD4+ lymphocytes in newly diagnosed patients with glioblastoma treated with radiation alone or in combination with temozolomide, and this attentuated CD4+ lymphocyte count is associated with increased infections and decreased survival." (PMID 26125449, 2015). "Furthermore, CD4+ T cells isolated from peripheral blood of glioblastoma patient showed marked IL-10 production against tumor cells indicating an enrichment of Tr1 cells within the peripheral CD4+ T cell pool in this patient." (PMID 23874336, 2013). "Taken together, in eight of nine (89%) POLE-mutated primary glioblastomas or spinal metastases, including three tumors harboring variants classified as likely pathogenic, the density of total CD3+ T lymphocytes and/or CD4+ or CD8+ subsets was increased compared to controls with WT POLE." (PMID 37990341, 2023). "The density of total CD3+ T lymphocytes and/or CD4+ or CD8+ subsets was increased in six of seven (86%) POLE-mutated primary glioblastomas, and that of CD68+ macrophages in three of seven (43%) POLE-mutated primary glioblastomas compared to the mean density in five POLE WT glioblastomas." (PMID 37990341, 2023). "In glioblastoma, a typical immunologically ‘cold’ tumor, the suppressive Treg cells were converted toward CD4 effector T cells by an agonistic antibody (αGITR), which promoted the cure rates in GBM models combined with PD1 antibodies." (PMID 36189283, 2022). "Similarly, to assess the correlation between the expression of c-Met and FasL on GSCs with peripheral circulating immune cells, PBMCs of the same glioblastoma patients and healthy controls were evaluated for CD4+, CD8+, and T reg (CD25 + FOXP3) through flow cytometry." (PMID 36299858, 2022). "Additionally, CD4+ Tcm, Tem and Tregs expressing CD49d (integrin α4) were enriched in glioblastoma." (PMID 35464424, 2022).
glioblastoma (continued). "Patients with glioblastoma (GBM) are locally and systemically immunosuppressed as lymphocyte counts, mainly CD4+, are reduced and T-cell proliferation, in response to interleukin-2 (IL-2), is impaired." (PMID 28107450, 2017). "The therapeutic efficacy of the cell-based vaccines in patients with glioma and glioblastoma is primarily driven by tumor antigen-specific CD8+ T cell activation, orchestrated by CD4+ T cell help." (PMID 41374974, 2025). "Specifically, in glioblastoma (GBM), LSM2 expression was positively correlated with tumour purity and neutrophil infiltration, but negatively correlated with CD4+ T cell infiltration." (PMID 40365337, 2025). "In contrast to human glioblastoma, the TIME of other types of intracranial tumors such as schwannoma are enriched in pro-inflammatory responses including CD4+ and CD8+ effector and memory T-cells and classic dendritic cells." (PMID 40161763, 2025). "Primary HLA-A*02+ glioblastoma cell lines led to activation of CD8+ PTPRZ1-TCR-T at various degrees and additionally activated CD4+ PTPRZ1-TCR-T in a moderate fashion." (PMID 39893177, 2025). "In PBMC-humanized mice bearing orthotopic glioblastoma xenografts, [64Cu]Cu-NOTA-IAB41 effectively visualized CD4-positive tumor-infiltrating lymphocytes in the brain, correlating with autoradiographic and histological findings." (PMID 41019666, 2025). "PTEN inhibits CD4+/CD8+T cells and dendritic cells while favoring M2 macrophages, Tregs, and MDSCs, participating in glioblastoma progression, metastasis, and immunity." (PMID 39206155, 2024). "In contrast, glioblastoma patients were mainly characterized by lower fractions of several T memory subsets, except for KLRG1+ CD4+ TTE, which were more abundant in the PB of glioblastoma patients in comparison to controls." (PMID 39497174, 2024). "IFNγ positivity was significantly increased when CD4+ and CD8+ T cells and NK cells from healthy donors and glioblastoma patients were stimulated with PMA and ionomycin." (PMID 39513882, 2024). "These pro-inhibitory changes are also correlated with reduced levels of the activation marker CD69 and the pro-inflammatory cytokine IFNγ in CD4+ and CD8+ T cells, as well as NK cells from glioblastoma patients." (PMID 39513882, 2024). "Conversely, our data demonstrate that CD4+ and CD8+ T cells from glioblastoma patients displayed significantly lower percentages of FOXO1 and BLIMP1 positivity compared to healthy controls." (PMID 39513882, 2024). "Here, we demonstrate that the percentage of intracellular BAT3 positivity is reduced in CD4+ and CD8+ T cells and NK cells from glioblastoma patients." (PMID 39513882, 2024). "CD4+ and CD8+ T cells and NK cells from glioblastoma patients displayed significantly lower percentages of BAT3 positivity compared to those from healthy donors, irrespective of stimulation." (PMID 39513882, 2024). "In summary, our data demonstrate the differential maintenance of TIM-3 surface expression on CD4+ and CD8+ T cells, as well as NK cells, from glioblastoma patients compared to cells from healthy donors following stimulation." (PMID 39513882, 2024). "Several conflicting reports have evaluated TIM-3 expression on CD4+ and CD8+ T cells in the glioblastoma setting." (PMID 39513882, 2024). "Subsequent reductions in the positivity of the cell activation marker CD69 and the key pro-inflammatory cytokine IFNγ were also observed in CD4+ and CD8+ T cells and NK cells from glioblastoma patients." (PMID 39513882, 2024). "Nonetheless, overall we still identified dysfunctional levels of TIM-3 and BAT3 on CD4+ and CD8+ T cells and NK cells from glioblastoma patients." (PMID 39513882, 2024). "Like CD4+ T-cell subsets, CCR5 was expressed by a high proportion of all CD8+ T-cell subsets and was significantly enriched for all CD8+ T-cell subsets in glioblastoma." (PMID 35464424, 2022).